KLHL13 (kelch like family member 13)
Description:
Substrate-specific adapter of a BCR (BTB-CUL3-RBX1) E3 ubiquitin-protein ligase complex required for mitotic progression and cytokinesis. The BCR(KLHL9-KLHL13) E3 ubiquitin ligase complex mediates the ubiquitination of AURKB and controls the dynamic behavior of AURKB on mitotic chromosomes and thereby coordinates faithful mitotic progression and completion of cytokinesis.
Synonyms: BKLHD2; FLJ10262; formerly KIAA1309
Tractability: Small molecule: it belongs to a druggable protein family. PROTAC: ubiquitination databases record sites on it.
Gene: Protein-coding gene on chromosome X (117,897,794 to 118,117,340, reverse strand). Ensembl gene ENSG00000003096.
Subcellular location (Human Protein Atlas): Cytosol
Pathways (Reactome):
Immune System: Antigen processing: Ubiquitination & Proteasome degradation
Metabolism of proteins: Neddylation
Gene Ontology:
Molecular function: protein binding; ubiquitin-protein transferase activity; ubiquitin-like ligase-substrate adaptor activity
Biological process: protein ubiquitination; regulation of cytokinesis; proteasome-mediated ubiquitin-dependent protein catabolic process
Cellular component: Cul3-RING ubiquitin ligase complex; cytosol
Homologues: Orthologues: pig KLHL13 (99% identical), guinea pig KLHL13 (99% identical), macaque KLHL13 (98% identical), chimpanzee KLHL13 (98% identical), rabbit KLHL13 (97% identical), rat Klhl13 (94% identical), mouse Klhl13 (93% identical), tropical clawed frog klhl13 (89% identical), zebrafish klhl13 (88% identical). Paralogues in human: KLHL9 (89% identical), KLHL26 (40% identical), KLHL36 (32% identical), KLHL31 (32% identical), KLHL14 (31% identical), KLHL32 (30% identical), KLHL22 (29% identical), KLHL34 (28% identical), KLHL5 (28% identical), KLHL4 (28% identical), KLHL15 (27% identical), KLHL1 (27% identical), and 42 more.
Diseases named in the same sentence as KLHL13 in open-access papers:
KLHL13 is named in the same sentence as 10 diseases in open-access papers, as found by Europe PMC text mining. Sharing a sentence is not in itself a finding about the gene and the disease. The quoted sentences say what the papers report.
Insulin resistance (2 papers, 2023 to 2024). Increased resistance towards insulin, that is, diminished effectiveness of insulin in reducing blood glucose levels. "Analogously, the insulin receptor substrate-1 has been implicated in regulating insulin resistance via proteasomal degradation mediated by KLHL9/KLHL13/CUL339." (PMID 38834545, 2024). "While the KLHL9/KLHL13/CUL3 complex has been primarily implicated in regulating cell cycles, insulin resistance and cancer, its role in infectious diseases has remained largely unexplored." (PMID 38834545, 2024).
colorectal cancer (1 paper, 2025). A primary or metastatic malignant neoplasm that affects the colon or rectum. "According to The Cancer Genome Atlas (TCGA) database, the decreased expression of KLF5, KLHL13, and CUL3 in colorectal cancer tissues was predictive of poorer overall survival." (PMID 41443421, 2025).
diabetes (1 paper, 2025). "Cancer tissues had lower levels of KLF5, KLHL13, and CUL3 but higher levels of CEP57L1 than paracarcinoma counterparts, which was exaggerated by the presence of diabetes." (PMID 41443421, 2025). "In a cohort of cancer patients, KLF5, KLHL13, and CUL3 levels were lower, but CA and CEP57L1 were higher in cancer tissues, compared with noncancerous counterparts, which were more obvious in those with diabetes." (PMID 41443421, 2025).
laryngeal carcinoma (1 paper, 2019). Carcinoma that arises from the laryngeal epithelium. "Assessment of these genes in clinical sub-cohorts of TCGA indicated that early stage tongue (MTFR1, C8ORF33, OTUD6B) and laryngeal cancers (TWISTNB, KLHL13 and UBE2Q1) were defined by distinct prognosticators." (PMID 31310629, 2019).
neuroblastoma (1 paper, 2020). Neuroblastoma (NB) is the most common solid, extracranial childhood tumor. "The four UHR-NB upregulated genes (ADAM22, GAL, KLHL13 and TWIST1) were all upregulated in MYCN amplified neuroblastoma in 5 additional cohorts." (PMID 32629858, 2020).
cancer (2 papers, 2018 to 2025). A tumor composed of atypical neoplastic, often pleomorphic cells that invade other tissues. "In addition, decreased expression of KLF5 (cancer stage II), KLHL13 (stages III and IV), and CUL3 (stages II and IV) correlated with advanced tumor staging." (PMID 41443421, 2025). "Eight of these had decreased expression in cancer (KLHL3, KLHL4, KLHL13, KLHL14, KLHL29, KLHL30, KLHL32, and KLHL33) while four genes (ENC1, KLHL12, KLHL17, and KLHL35) had patterns of up-regulated gene expression." (PMID 30647843, 2018).
tumor (2 papers, 2020 to 2025). "Moreover, we demonstrated that two of the four upregulated genes (AMAM22 and TWIST1) were positively correlated with tumor stage in two independent cohorts, and KLHL13 was upregulated in subjects lacking of telomere maintenance, indicating the clinical relevance of the UHR-NB upregulated genes." (PMID 32629858, 2020).
infection (1 paper, 2024). The state of being infected such as from the introduction of a foreign agent such as serum, vaccine, antigenic substance or organism. "Nevertheless, the mRNA level of Immt showed no significant changes no matter when Cul3, Klhl9 or Klhl13 was knocked down after B. pseudomallei WT or ΔbipD infection." (PMID 38834545, 2024).
infectious disease (1 paper, 2024). A disorder directly resulting from the presence and activity of a microbial, viral, or parasitic agent in humans. "Although evidently not involved in regulation of infectious diseases, KLHL9/KLHL13/CUL3 E3 ligase complex was essential for BipD-dependent ubiquitination of mitochondria in mouse macrophages." (PMID 38834545, 2024).
KLHL13 also shares sentences with these, for which no sentence is quoted: glioblastoma (1 paper).